RRN3 (RNA polymerase I transcription factor RRN3)
Description:
Required for efficient transcription initiation by RNA polymerase I (Pol I). Required for the formation of the competent pre-initiation complex (PIC).
Synonyms: TIF-IA; TIFIA; DKFZp566E104; A-270G1.2
Tractability: PROTAC: ubiquitination databases record sites on it.
Gene: Protein-coding gene on chromosome 16 (15,060,022 to 15,094,311, reverse strand). Ensembl gene ENSG00000085721.
Subcellular location: Nucleus, nucleolus
Subcellular location (Human Protein Atlas): Nucleoli rim
Pathways (Reactome):
Gene expression (Transcription): RNA Polymerase I Promoter Escape; RNA Polymerase I Transcription Initiation
Gene Ontology:
Molecular function: protein binding; RNA polymerase I core promoter sequence-specific DNA binding; RNA polymerase I general transcription initiation factor activity; RNA polymerase I core binding; RNA polymerase binding
Biological process: transcription initiation at RNA polymerase I promoter; RNA polymerase I preinitiation complex assembly; transcription by RNA polymerase I
Cellular component: nucleolus; nucleoplasm; nucleus
Genetic constraint (gnomAD): Loss-of-function variants: 30 observed, 54.35 expected, observed/expected ratio (o/e) 0.55, 90% interval 0.41 to 0.75. The upper end of that interval is the gene's LOEUF score, 0.75, which puts it in group 3 of 6, group 1 being the genes least tolerant of losing a copy. Missense variants: 610 observed, 627.12 expected, observed/expected ratio (o/e) 0.97, 90% interval 0.91 to 1.04. Synonymous variants: 229 observed, 222.52 expected, observed/expected ratio (o/e) 1.03, 90% interval 0.92 to 1.15.
Homologues: Orthologues: chimpanzee RRN3 (99% identical), macaque RRN3 (95% identical), dog RRN3 (91% identical), guinea pig RRN3 (91% identical), pig RRN3 (90% identical), mouse Rrn3 (88% identical), rat Rrn3 (87% identical), tropical clawed frog rrn3 (65% identical), zebrafish rrn3 (59% identical), Drosophila melanogaster Tif-IA (30% identical), Caenorhabditis elegans tif-1A (24% identical).
Diseases named in the same sentence as RRN3 in open-access papers:
RRN3 is named in the same sentence as 23 diseases in open-access papers, as found by Europe PMC text mining. Sharing a sentence is not in itself a finding about the gene and the disease. The quoted sentences say what the papers report.
breast carcinoma (3 papers, 2021 to 2024). "Manipulating RRN3 has been shown to impact mammary epithelial morphogenetic processes in breast cancer." (PMID 39049162, 2024).
lung carcinoma (1 paper, 2024). "Investigating the Catalogue Of Somatic Mutations In Cancer, RRN3 is found mutated in about 1% of sample, and is found overexpressed mostly in breast, central nervous system, kidney, pancreas and lung cancer." (PMID 39049162, 2024).
meningioma (1 paper, 2020). A generally slow growing tumor attached to the dura mater. "Among the 2N patients, we detected six genes (POLR3F, SEC23B, ZNF133, C16orf45, RRN3, and NTAN1) which were overexpressed after irradiation and were duplicated in the genome of ALL patients with the second independent cancer being either meningioma or thyroid carcinoma." (PMID 32577795, 2020).
ovarian carcinoma (1 paper, 2025). A malignant neoplasm originating from the surface ovarian epithelium. "Through a genome-wide screening based on an abnormal transcriptional readthrough event favoring the malignant progression of ovarian carcinoma (OC), we identified novel mRNA processing regulators including RRN3, an essential factor for the transcriptional initiation of rRNA." (PMID 41271632, 2025).
pancreatic cancer (1 paper, 2024). "In cancer cells, high RRN3 expression is associated with malignant characteristics and poor prognosis, as seen in pancreatic cancer." (PMID 39049162, 2024).
renal carcinoma (1 paper, 2016). A carcinoma arising from the epithelium of the renal parenchyma or the renal pelvis. "However, a RNA polymerase I-specific transcription initiation factor (RRN3) and PDXDC1, a gene with carboxylase activity associated with diverse phenotypes including renal carcinoma and sensorineural hearing loss were also either proximate to or overlapping the peak in CMS1-FDR signal." (PMID 26943675, 2016).
cancer (8 papers, 2007 to 2026). A tumor composed of atypical neoplastic, often pleomorphic cells that invade other tissues. "Consistent with this, a peptide mimicking the interaction region of RPA43 is able to compete for RRN3 binding and inhibit Pol I transcription and studies using novel peptide deliver approaches of the RRN3 peptide for cancer treatment are already underway (L Rothblum, personal communication)." (PMID 31973211, 2020). "Furthermore, a possible contribution of deregulated Pol I and/or pre-rRNA accumulation to genome stability was not documented previously, and could suggest a role for Rrn3 in genome stability in both normal and pathological contexts, such as cancer." (PMID 39049162, 2024).
tumor (4 papers, 2018 to 2026). "Clinical validation showed that RRN3 was upregulated in GC tissues and associated with several clinicopathological features related to tumor progression." (PMID 42211503, 2026). "In GC, RRN3 expression was associated with RNA methylation regulators, immune checkpoint genes, tumor mutation burden, microsatellite instability, immune cell infiltration, and drug-response-related signatures." (PMID 42211503, 2026). "The subcellular localization of RRN3 in the tumor xenografts were verified by IF staining, which confirmed that the nuclear plasma-localized RRN3S199D induced a higher level of autophagy, as evidenced by both LC3 IF and OPTN IHC analyses." (PMID 41271632, 2025).
RRN3 also shares sentences with these, for which no sentence is quoted: colorectal tumors (2 papers); leukemia (2); aneurysm (1); asthma (1); colon cancer (1); gallbladder cancer (1); gastric cancer (1); HCMV infection (1); Huntington disease (1); infection (1); lymphoma (1); medulloblastoma (1); neurodegenerative disease (1); sensorineural hearing loss (1); thyroid carcinoma (1).